TRPV4 (transient receptor potential cation channel subfamily V member 4)
Diseases named in the same sentence as TRPV4 in open-access papers (continued):
Sharing a sentence is not in itself a finding about the gene and the disease.
ulcers (4 papers, 2019 to 2022). "We also tested the expression of TRPV4 in the duodenum of mice with duodenal ulcer, and the results showed that TRPV4 was highly expressed in the duodenum of mice with ulcers compared with control group." (PMID 35028313, 2022). "Our results suggest that TRPV4 and adenosine could be promising novel therapeutic targets for esophageal erosions and ulcers." (PMID 32647282, 2020).
Vocal cord paralysis (4 papers, 2015 to 2025). A loss of the ability to move the vocal folds. "Vocal cord paralysis has been considered to be a key clinical aspect for the diagnosis of SP-SMA due to TRPV4 mutation." (PMID 39457418, 2024). "The TRPV4-related neurological disease group has now been characterized by muscle weakness, vocal cord paralysis, and bone abnormalities." (PMID 39457418, 2024). "Other common features of TRPV4-related neuromuscular diseases include vocal cord paralysis, scoliosis, and/or arthrogryposis." (PMID 39457418, 2024). "Clinical clues to pinpoint the causative gene from the heterogeneous CMT2 and AR‐CMT2 group included pyramidal signs in SACS, MTRFR, and HSPB1, vocal cord paralysis in TRPV4, intellectual disability in MCM3AP, late disease onset in MME, in accordance with previous reports." (PMID 39776111, 2025).
allergic asthma (3 papers, 2023 to 2026). A asthma with a basis in a pathological type I hypersensitivity reaction. "In an mice model of allergic asthma, it has been observed that TRPV4 can modulate airway wall thickness, collagen synthesis, recruitment of goblet cells, expression of TGF-β and fibrosis remodeling in the airways." (PMID 37841931, 2023). "Allergic asthma severity was evaluated through histopathological changes, pulmonary function, Th1/Th2 balance, mucus hypersecretion, and inflammatory factor levels, alongside the activation of TRPV4 and MAPK signaling pathways (ERK, p38MAPK, and JNK)." (PMID 41893487, 2026). "Studies have provided evidence that TRPV4 plays a regulatory role in allergic asthma." (PMID 37841931, 2023). "Additionally, another study using a mouse model of allergic asthma induced by ovalbumin found that exposure to high relative humidity and formaldehyde intensified the activation of TRPV4 in the lungs." (PMID 37841931, 2023). "In a mouse model of allergic asthma induced by OVA, the TRPV4-p38 MAPK pathway is activated." (PMID 38543079, 2024).
Alzheimer disease (3 papers, 2022 to 2026). A progressive, neurodegenerative disease characterized by loss of function and death of nerve cells in several areas of the brain leading to loss of cognitive function such as memory and language. "Collectively, these findings strongly suggest that the activation of TRPV4 may play an important role in the pathogenesis and progression of Alzheimer’s disease." (PMID 39333347, 2025). "Furthermore, TRPV4 was significantly upregulated in early-onset Alzheimer's disease patients." (PMID 41792369, 2026). "Notably, in the context of Alzheimer’s disease, research conducted by Du and colleagues revealed that the activation of TRPV4 led to an increase in tau phosphorylation within the cortex and hippocampus of the P301S tauopathy mouse model, exacerbating cognitive decline." (PMID 39333347, 2025).
Anxiety (3 papers, 2022 to 2025). Intense feelings of nervousness, tension, or panic often arise in response to interpersonal stresses. "Dex improves ICH-induced anxiety-like behaviors in mice, and the mechanism might be associated with the inhibition of TRPV4-channel opening." (PMID 35431940, 2022). "Our data showed that the opening of TRPV4 channels activated by GSK1016790A heavily abolished the beneficial effects of Dex administration in attenuating anxiety-like behaviors." (PMID 35431940, 2022). "Taken together, these results indicate that Dex treatment alleviated ICH-induced anxiety-behaviors via modulation of TRPV4 channels in the astrocyte." (PMID 35431940, 2022). "Our data showed that the agonist of TRPV4 abolished the improvement of anxiety-like behaviors induced by ICH exposure." (PMID 35431940, 2022). "This study examines whether Dex improved ICH-induced anxiety via the inhibition of TRPV4 channel opening." (PMID 35431940, 2022).
Arrhythmia (3 papers, 2021 to 2024). Any cardiac rhythm other than the normal sinus rhythm. "Interestingly, these pathologies are often associated with cardiac dysfunction and arrhythmias However, a direct link between mutated TRPV4 channels and the cardiac phenotype remains to be demonstrated." (PMID 37371124, 2023). "TRPV4−/− mice receiving isoproterenol treatment had preserved cardiac dimensions and function and exhibited significantly less collagen deposition and arrhythmia inducibility compared to TRPV4+/+." (PMID 38338818, 2024).
atrial fibrillation (3 papers, 2020 to 2023). A disorder characterized by an electrocardiographic finding of a supraventricular arrhythmia characterized by the replacement of consistent P waves by rapid oscillations or fibrillatory waves that vary in size, shape and timing and are accompanied by an irregular ventricular response. "Since the TRPV4 channels are expressed in native cardiac cells, including atrial cardiomyocytes, their implication in atrial fibrillation was evaluated." (PMID 37371124, 2023). "In a model of a rat sterile pericarditis-related atrial fibrillation phenotype, the TRPV4 expression level markedly increased within the atrial tissue over 2 weeks after surgery compared to the sham condition." (PMID 37371124, 2023). "Pacing induced atrial fibrillation (AF) 3days post-pericardiotomy was ameliorated in both frequency and duration by treatment with the TRPV4-specific inhibitor GSK2193874." (PMID 34867442, 2021). "TRPV4 expression increases under certain pathophysiological conditions, such as aging, pressure overload, ischemia–reperfusion, increased membrane tension and pericarditis in rats and patients with atrial fibrillation." (PMID 37371124, 2023). "TRPV4 blockade prevents abnormal changes in atrial myocyte electrophysiology and ameliorated atrial fibrosis in rats and might be a promising strategy to treat atrial fibrillation." (PMID 33119551, 2020).
autosomal recessive polycystic kidney disease (3 papers, 2011 to 2023). An inherited disorder characterized by the development of cysts affecting the collecting ducts. "However, in Polycystic Kidney And Hepatic Disease 1/polyductin ((PKHD1), mutated in ARPKD) mutant pck rats, activation of an otherwise deficient Trpv-4 protein helped attenuate cystogenesis." (PMID 34828368, 2021). "In patients with polycystic liver diseases (autosomal-recessive polycystic kidney disease and autosomal-dominant polycystic kidney disease) TRPV4 is overexpressed in cholangiocytes, a finding that is reproduced in polycystic kidney rats, a model for autosomal-recessive polycystic kidney disease." (PMID 21420431, 2011).
bladder disorders (3 papers, 2017 to 2024). "It was concluded that TRPV4 channel could be a promising target for bladder function disorders but so far information concerning effects of TRPV4 on human LUT does not seem to be available." (PMID 31121962, 2019).
Charcot-Marie-Tooth disease (3 papers, 2006 to 2025). An inherited degenerative disorder involving the peripheral nerves. "The TRPV4-related peripheral neuropathies can be primarily categorized into three groups: Charcot-Marie-Tooth disease (CMT) type 2C, scapuloperoneal spinal muscular atrophy, and distal hereditary SMA (CDSMA)." (PMID 39333347, 2025). "The ANO3 missense variant c.638C>T was reported in ClinVar as VUS without phenotype and TRPV4 c.2336+1G>A as VUS for Charcot-Marie-Tooth disease." (PMID 35806193, 2022).
chronic asthma (3 papers, 2017 to 2024). An asthma that is characterized by the development of persistent airway inflammation and recurrent attacks of breathlessness and wheezing, which vary in severity and frequency. "In addition, it has been suggested that the TRPV4 channel is involved in the proliferation of bronchial smooth muscle cells, which is linked to chronic asthma." (PMID 38543079, 2024). "TRPV4 channels participate in the KCa3.1-regulated proliferation of human bronchial smooth muscle cells in the process of chronic asthma, indicating that it is a potential therapeutic target for chronic asthma treatment." (PMID 33981725, 2021).
Crohn disease (3 papers, 2020 to 2025). A gastrointestinal disorder characterized by chronic inflammation involving all layers of the intestinal wall, noncaseating granulomas affecting the intestinal wall and regional lymph nodes, and transmural fibrosis. "Given TRPV4’s pro-inflammatory role in the gut, therapeutic delivery of miR-203 mimics represents a promising strategy to attenuate TRPV4-mediated pathology in Crohn’s disease." (PMID 41002400, 2025).
deafness (3 papers, 2012 to 2022). An inherited or acquired condition characterized by the complete loss of the ability to hear from one or both ears. "TRPV4 deletion in mice is associated with defective responses to noxious mechanical pressure and late-onset deafness." (PMID 22724068, 2012). "Although TRPV4 inhibition would be an interesting target for pain, deafness, incontinence, and osmoregulation, deficits were observed in TRPV4-knockout mice, which questions the clinical utility of TRPV4 antagonists." (PMID 36614146, 2022). "Ion channels linked to deafness include a number of potassium channels and both TRPML3 and TRPV4, although none of these channels are a strong candidate for primary mechanotransduction, because of their localization or biophysical properties." (PMID 22724068, 2012).
dermatitis (3 papers, 2018 to 2025). An inflammatory process affecting the skin. "To further determine its selectivity, we tested the inhibition rate of fluoxetine on other dermatitis-related TRP channels transiently expressed in HEK293T cells, such as TRPV1, TRPV4, TRPA1, and TRPM8." (PMID 40699677, 2025).
diabetic retinopathy (3 papers, 2017 to 2024). "TRPV4 is also involved in the development of diabetic retinopathy due to its role in the regulation of membrane potential and responses to osmotic pressure in the retinal neurons." (PMID 39517820, 2024). "TRPV4 knock-out or inhibition shows promise in preventing diabetic retinopathy complications, again showing the potential of TRPV4 targeting in therapeutic approaches." (PMID 39517820, 2024). "In conclusion, our novel data indicate that TRPV4-signaling can be recruited as a novel target to combat diabetic retinopathy, which is characterized by permeability changes that can be attenuated by endogenous vasoinhibins, which combine synergistically with selective TRPV4 blockers." (PMID 29026201, 2017). "Thus, the TRPV4 and MCP-1-induced macrophage recruitment might be related to the disease progression of diabetic retinopathy or retinal vein occlusion." (PMID 30143574, 2018).
emphysema (3 papers, 2020 to 2022). "As SP-C-deficient mice show emphysema-like changes similar to TRPV4-/- mice, this phenotype may rather be responsible for the higher edema formation." (PMID 33917551, 2021). "Most interestingly, the emphysema-like changes in lung morphology were also detected in SP-C–deficient mice, raising the possibility that reduced SP-C levels in TRPV4–/– ATII cells may also contribute to the phenotype." (PMID 32931478, 2020). "TRPV4–/– mice showed emphysema-like lung structure and altered lung function." (PMID 32931478, 2020). "In conclusion, adult TRPV4–/– mice showed emphysema-like changes in their lungs, which may be responsible for altered lung function." (PMID 32931478, 2020). "Importantly, AT2 cells of TRPV4-/- mice showed a decreased production of pro-surfactant protein C, a precursor of surfactant protein-C (SP-C), secreted from these cells and older mice exhibited emphysema-like changes in their lung structure." (PMID 33917551, 2021). "Thus, e.g., TRPV4 channels are essential for alveolar epithelial barrier function as protection from lung edema and lungs from mice lacking TRPC6 are protected from lung ischaemia-reperfusion-induced oedema (LIRE), while magnesium deficiency in TRPM6 results in severe emphysema." (PMID 35053420, 2022).
endometriosis (3 papers, 2018 to 2021). The growth of functional endometrial tissue in anatomic sites outside the uterine body. "GSK (10 nM) was used as a selective TRPV4 agonist, which showed a rapid and reversible calcium influx of 496 ± 366 nM in endometriosis-derived hESC and 484 ± 277 nM in control hESC, in, respectively, 37 ± 18% (total of 305 cells) and 28 + 16% of the cells (total of 241 cells)." (PMID 30134548, 2018). "Additionally, TRPV2, TRPV4, TRPC1/4, and TRPC6 were found in human endometrial stromal cells (hESCs) from patients with endometriosis." (PMID 34337010, 2021). "Additionally, and in line with previous reports of control patients, TRPV2, TRPV4, TRPC1/4, and TRPC6 were present in human endometrial stromal cells (hESC) from endometriosis patients both at the molecular and functional level." (PMID 30134548, 2018).
esophageal cancer (3 papers, 2019 to 2023). A primary or metastatic malignant neoplasm involving the esophagus. "Hypothetically, low expression of the TRPV4 channel in esophageal cancer cells decreases the release of ATP and, hence, reduces formation of adenosine." (PMID 35562940, 2022). "The TRPV4 channel was shown to be overexpressed in colorectal, lung, and gastric cancer cells relative to the respective healthy cells, but in prostate, skin, and esophageal cancer cells, TRPV4 channel expression was lower relative to healthy cells." (PMID 35562940, 2022).
esophageal squamous cell carcinoma (3 papers, 2019 to 2023). Esophageal squamous cell carcinoma (ESCC) is a type of esophageal carcinoma (EC) that can affect any part of the esophagus, but is usually located in the upper or middle third. "Previous studies reported that TRPV4 was involved in tumorigenesis in different kinds of cancers, such as in esophageal squamous cell carcinoma, where we can see an upregulation of TRPV4." (PMID 34199609, 2021).
experimental autoimmune encephalomyelitis (3 papers, 2020 to 2024). An autoimmune demyelinating disease of the central nervous system that is produced experimentally in animals by the injection of homogenized brain or spinal cord in Freund's adjuvant. "specifically compared TRPV4−/− mice and littermates in experimental autoimmune encephalomyelitis (EAE), a well-known animal model for MS, and did not observe apparent difference in clinical score or BBB leakage." (PMID 38521959, 2024).
hearing loss (3 papers, 2019 to 2025). "In our French series, five patients were detected with a variant in TRPV4, but only one of them was referred with diagnosed hearing loss." (PMID 31393079, 2019). "The Trpv4 gene is associated with Deafness, autosomal dominant, 25, a locus that is linked to dominant nonsyndromic hereditary hearing impairment." (PMID 31866822, 2019). "The reasons for the contradictory role of TRPV4 in drug-induced hearing loss are likely complex." (PMID 40688696, 2025). "This suggests that TRPV4 can facilitate drug uptake, leading to hair cell damage and subsequent hearing impairment." (PMID 40688696, 2025). "Based on these observations, it was suggested that TRPV3 and TRPV4 play an important role in neuroprotection while TRPV1 and TRPV2 are involved in the pathology of hearing loss." (PMID 31866822, 2019).
Hyperkalemia (3 papers, 2021 to 2024). An abnormally increased potassium concentration in the blood. "Consistently, deletion of either BK or TRPV4 leads to hyperkalemia, when animals are subjected to high K+ diet." (PMID 34204757, 2021). "Importantly, TRPV4-/- mice develop renal K+ retention and hyperkalemia when fed with high K+ diet, suggesting its critical role in maintaining systemic K+ balance." (PMID 34204757, 2021). "Overall, the lack of AQP4 channels had the opposite effects on volume changes in the LRA and HRA subpopulations, the lack of TRPV4 channels affected only the LRA, resulting in lesser volume changes in response to hyperkalemia." (PMID 38818517, 2024).
influenza (3 papers, 2021 to 2025). An acute viral infection of the respiratory tract, occurring in isolated cases, in epidemics, or in pandemics; it is caused by serologically different strains of viruses (influenzaviruses) designated A, B, and C, has a 3-day incubation period, and usually lasts for 3 to 10 days. "In summary, our study presents the first predictive model for identifying TRPV4 inhibitors, underscoring TRPV4 inhibition as a promising strategy for antiviral drug development against influenza." (PMID 39941149, 2025). "Little is known about the function of the TRPV4 channel during influenza infection, but these results suggest that TRPV4 plays a key role for preventing the exacerbation of pneumococcal infections." (PMID 34804016, 2021). "Therefore, TRPV4 and RAGE may serve as new targets for therapeutic intervention in patients infected with influenza and other potential pandemic viruses that cause life-threatening lung inflammation." (PMID 35396513, 2022).
irritable bowel syndrome (3 papers, 2017 to 2024). Irritable bowel syndrome (IBS) is a chronic functional condition of the lower gastrointestinal (GI) tract characterized by abdominal pain or discomfort and disordered bowel habit (diarrhea, constipation, or fluctuation between the two). "Additionally, PAR2 coupling with TRPV4 has been reported to amplify the pro-inflammatory state via calcium release, leading to a chronic hyperexcitability of nociceptors, especially implicated in irritable bowel syndrome (IBS)." (PMID 39201414, 2024). "Potentiation (sensitization) of cellular responses by histamine has been reported in patients with irritable bowel syndrome, in which pre-exposure of sensory neurons from the colon to histamine increases TRPV4-mediated intracellular signaling, thereby increasing visceral hypersensitivity." (PMID 28074918, 2017).
nasopharyngeal carcinoma (3 papers, 2022 to 2025). A carcinoma arising from the nasopharyngeal epithelium. "Research has found that TRPV4 expression is significantly elevated in nasopharyngeal carcinoma tissues and human nasopharyngeal carcinoma cell lines.TRPV4 stimulates tumor occurrence through Ca2+/NFAT4-signaling." (PMID 39759147, 2024). "However, it is unclear whether matrix stiffness regulates the invasiveness of nasopharyngeal carcinoma (NPC) cells through TRPV4." (PMID 39895789, 2025). "However, little is known regarding the effect of TRPV4 in nasopharyngeal carcinoma (NPC), a highly prevalent malignancy in Southern China and Southeast Asia." (PMID 36619170, 2022).
oropharyngeal dysphagia (3 papers, 2023 to 2026). "Our study provides enhanced understanding of TRPV4-mediated sensory regulation of swallowing and suggests that TRPV4 is a potential therapeutic target for oropharyngeal dysphagia." (PMID 42052238, 2026). "The results may indicate TRPV4 as a target to develop a pharmacological treatment for the management of oropharyngeal dysphagia." (PMID 36909278, 2023). "TRPV4 is a potential pharmacological target for the management of oropharyngeal dysphagia." (PMID 36909278, 2023). "TRPV4 can be pharmacologically targeted to facilitate swallowing to manage oropharyngeal dysphagia." (PMID 36909278, 2023).
polycystic kidney (3 papers, 2011 to 2023). "TRPV4 agonists attenuate the growth of cultured cholangiocytes from polycystic kidney rats and retard the formation of cysts in culture, whereas the growth of cholangiocytes from normal rats is not altered." (PMID 21420431, 2011).